PDPN (podoplanin)
Diseases named in the same sentence as PDPN in open-access papers (continued):
Sharing a sentence is not in itself a finding about the gene and the disease.
tumor (continued). "In agreement, immunofluorescent staining of GC patient tumor samples revealed that CCL2 was abundantly expressed in PDPN(+) CAFs." (PMID 39764562, 2025). "In a co-culture assay, T cells, in the presence of PDGFRα/β+PDPN (podoplanin) + CAFs, exhibited low cytotoxicity towards co-cultured tumour cells." (PMID 39780187, 2025). "As anticipated, treating PDPN(+) CAFs with either perifosine or Bay117082 significantly inhibited the tumor growth." (PMID 39764562, 2025). "Immunochemistry of tumor tissues harvested earlier also confirmed that the group with PDPN(+) CAFs expressed higher levels of PDPN, CCL2, and p‐AKT in the tumor stroma compared to the PDPN(−) CAFs group and NC group." (PMID 39764562, 2025). "The bidirectional signaling between platelet C-type lectin-like receptor 2 (CLEC-2) and podoplanin on tumor cells induces platelet activation, aggregation, and the secretion of bioactive molecules, thereby enhancing tumor cell survival." (PMID 39852571, 2025). "Significant correlations between the expression of POSTN and PDPN and the number of positive cells and/or the intensity of the reaction were observed within each tumour type, as presented in the following paragraphs." (PMID 41361308, 2025). "We compared the percentages of PD-L1+CD31+/CD31+ and PD-L1+Podoplanin+/Podoplanin+ cells on days 10, 15, and 22 after tumor cell inoculation." (PMID 40809013, 2025). "CY12-RP2 resulted in a 60.6% reduction in tumor growth in immunocompetent murine models and reversed immune evasion by attenuating PDPN-dependent, β-catenin-mediated upregulation of PD-L1." (PMID 41573582, 2025). "When using AKT inhibitors perifosine and LY294002, both HUVECs treated with CCL2 and tumor‐burdened mice injected with PDPN(+) CAFs and GC cells maintained their proangiogenic properties." (PMID 39764562, 2025). "This study identifies podoplanin (PDPN), a transmembrane glycoprotein enriched in CAFs, as highly expressed in the CRC TME, in particular surrounding the tumor, and associated with macrophage infiltration and cancer progression." (PMID 40842027, 2025). "Within tumor cells, PDPN interacts with the ERM protein family, contributing to epithelial–mesenchymal transition." (PMID 41573582, 2025). "Platelets become locally activated through the interaction of podoplanin with C-type lectin-like immune receptor 2 (CLEC-2) on tumor cells, as well as high-mobility group box 1 (HMGB1) with TLR4." (PMID 40723273, 2025). "PDPN positivity in the tumor cell membranes was observed in 100%, 2%, and 43.5% of EMPM, LAC, and LSCC cases, respectively." (PMID 40428290, 2025). "Pharmacologic targeting of this PDPN–β-catenin–PD-L1 pathway with the inhibitory peptide CY12-RP2 disrupts PDPN-driven immunosuppression within the tumor microenvironment, positioning this approach as a promising strategy for melanoma therapy." (PMID 41573582, 2025). "In parallel, the clustering of podoplanin by platelet CLEC-2 modulates multiple signaling pathways that regulate tumor cell migration and invasion 12,21." (PMID 41209555, 2025). "Upon detection of PDPN positivity on the tumor cell membrane, the slide was directly subjected to FE-SEM analysis using the NanoSuit-CLEM method." (PMID 40428290, 2025). "If PDPN positivity is detected on the tumor cell membrane, the slide can be directly processed for FE-SEM analysis using the NanoSuit-CLEM method." (PMID 40428290, 2025). "Preclinical studies have demonstrated the efficacy of targeting PDPN to inhibit tumor progression and metastasis." (PMID 40149492, 2025). "Since PDPN co-stains fibroblasts within the tumor, it is possible that the transient increase in PDPN+ area coverage we saw in the tumor is reflective of this change in the population." (PMID 39998766, 2025). "Collectively these data underscore that PDPN(+) CAFs are a prominent proangiogenic factor in GC, playing a critical role in promoting tumor growth and vascularization." (PMID 39764562, 2025).
tumor (continued). "In this study, the immunohistochemical analysis of PDPN expression in 11 cases of EMPM, 100 cases of LAC, and 23 cases of LSCC revealed significant differences in PDPN positivity among these tumor types." (PMID 40428290, 2025). "Mechanistically, PDPN associates with CLEC-2 receptors on platelets via its extracellular PLAG3 domain, thereby facilitating platelet activation and promoting tumor cell invasion." (PMID 41573582, 2025). "While we observed down regulation of Calretinin in all primary cells compared to the tumor tissues, the remaining markers for mesothelial cell origin, including Podoplanin and WT1, remained positive." (PMID 39920655, 2025). "Significantly increased PDPN+ area coverage and lymphatic cross-sectional vessel density were observed within the viable tumor after SA-HFIRE." (PMID 39998766, 2025). "Specifically, when μNMR is combined with multiple tumor markers like EGFR, EGFRvIII, PDPN, and IDH1-R132H, the overall diagnostic accuracy has been elevated to over 90%." (PMID 39465690, 2025). "Scientific reports have shown that POSTN and PDPN proteins play an important role in the carcinogenesis of various types of neoplasms in both humans and animals." (PMID 41361308, 2025). "PDPN is upregulated in a wide range of cancers, where it is overexpressed not only in tumor cells but also in stromal cells, particularly CAFs." (PMID 40842027, 2025). "PDPN expression was weak in 37 tumours (60.7%), moderate in 6 (9.8%) tumours and intense in 1 (1.6%) tumours." (PMID 41361308, 2025). "F. rodentium produces metabolites that downregulate PDPN to promote the anti-tumor immunity of CD8+ T cells, which inhibits the progression of CRC." (PMID 40693815, 2025). "Immunofluorescent staining for CD31 revealed that blocking the AKT/IKK/NF‐κB signaling pathway in PDPN(+) CAFs resulted in a substantial decrease in tumor vessel density." (PMID 39764562, 2025). "Here, we confirm that CCL2 secreted from PDPN(+) CAFs acts as a powerful mediator between CAFs and ECs to facilitate tumor angiogenesis." (PMID 39764562, 2025). "Consistent with our analysis that IDH1 loss of function mutations is associated with lower lymph vessel signature, upregulation of PDPN induces lymphangiogenesis and metastasis in tumor." (PMID 38241355, 2024). "Conversely, knocking down EBP1 suppressed PDPN transcription, invasiveness, and tumor formation in immunodeficient mice." (PMID 40741180, 2024). "This study demonstrated that semaphorin 7A (SEMA7A) expression on tumor cells induces expression of PDPN on macrophages, which promotes migration of PDPN+ macrophages to lymphatic endothelial cell structures, thereby promoting lymphangiogenesis." (PMID 38426622, 2024). "Podoplanin on tumour cells activates the receptor CLEC-2, which recruits Syk to phosphorylate tyrosine in CLEC-2." (PMID 38561690, 2024). "Interaction with ERM proteins is crucial for PDPN-induced epithelial-to-mesenchymal transition (EMT) in tumor progression as well as lymphangiogenesis and immune responses." (PMID 39594582, 2024). "We observed increased colocalization of CX3CR1+ cells and PDPN+ structures with increasing lymph-circulating tumor cells after CX3CL1 overexpression." (PMID 38775151, 2024). "PDPN promotes tumor metastasis through the recruitment of the ERM complex, which remodels actin cytoskeletons and EMT." (PMID 39594582, 2024). "The results showed that out of the 151 tumor specimens, 33 had high expression, 47 had medium expression, and 71 had low expression of PDPN." (PMID 39682237, 2024). "PDPN contributes to malignant tumor progression by regulating signaling that controls cell proliferation, differentiation, migration, invasion, epithelial–mesenchymal transition, and stemness." (PMID 39487962, 2024). "The results indicated that PDPN expression in cellular tumor (CT) was significantly higher than infiltrating tumor (IT) and leading edge (LE) (p = 0.0012, p < 0.0001, respectively)." (PMID 38470096, 2024).
tumor (continued). "Selective blockage of PDPN-mediated platelet–tumor cell interaction is a plausible strategy for inhibiting metastases." (PMID 39451677, 2024). "The phenotypical and structural remodeling of the PDPN+ FRC network appears to be driven by tumor-derived factors." (PMID 38038708, 2024). "CAFs (α-SMA+) and lymphatic vessels (PDPN+ or LYVE1+) were abundant in CCA tumor tissues compared with those in normal liver tissues and para-tumoral tissues, and were spatially close to each other, suggesting an interaction between them." (PMID 37307823, 2024). "Intratumoral PDPN expression patterns were diffuse, heterogenous, and predominantly membrane-bound on tumor cells." (PMID 40741180, 2024). "The PDPN extracellular domain such as PLAG1, PLAG2, and PLAG3, are associated with tumor-induced platelet aggregation." (PMID 38561690, 2024). "PDPN expression levels varied among tumor types in vivo, with the highest expression in MOC2 tumors compared to LL/2 and MC38 tumors but absent in MOC2 in vitro-cultured cells." (PMID 38275890, 2024). "PMab-117-mG2a also elicited more potent ADCC against endogenous PDPN expressing tumor PC-10 (42.1% cytotoxicity; p < 0.01) and LN319 (23.9% cytotoxicity; p < 0.01) cells." (PMID 39594582, 2024). "When CLEC-2 was produced in the laboratory, it was found to inhibit platelet aggregation triggered by tumor cells or lymphatic endothelial cells expressing PDPN." (PMID 39682237, 2024). "Although various anti-PDPN antibodies have been developed, validation using tumor cells that endogenously express PDPPN remains limited." (PMID 38504248, 2024). "PDPN is expressed in CAFs, lymphatic endothelium, and inflammatory macrophages in the tumor microenvironment." (PMID 39403603, 2024). "Anti-FAP NIR-PIT effectively depleted FAP+ CAFs, as well as FAP+ myeloid cells, and suppressed tumor growth, whereas anti-podoplanin NIR-PIT was ineffective." (PMID 38275890, 2024). "PDPN expression is significantly upregulated in inflammation and cancer, and function as a good predictor of tumour malignancy and a target for biological therapy, but it is also expressed in macrophages, T cells and epithelial cells." (PMID 38158643, 2024). "PDPN interacts with Gal-8 on lymphatic ECs to promote new lymph vessel formation and the migration of tumor cells through the lymphatic system." (PMID 38426109, 2024). "Various approaches for the blockage of the PDPN/CLEC-2 signaling axis and PDPN-induced platelet–tumor cell interactions have been developed." (PMID 39451677, 2024). "In this study, we performed immunohistochemical analysis of PDPN expression in CAF (CAF‐PDPN), programmed death‐ligand 1 (PD‐L1) expression in the tumor (tumoral PD‐L1), and PD‐L1 expression in the stroma (stromal PD‐L1)." (PMID 39487962, 2024). "The FAP+PDPN+ population of CAFs is enriched at the outer edge of the tumor, in close contact with T cells, whereas the FAP+PDPN− population of cancer-associated pericytes (CAPs) is located around the vessels." (PMID 38715072, 2024). "A FAP+PDPN+ population of CAFs, which are located at the outer edge of the tumour, contributes to inhibiting the proliferation of T cells, while FAP+PDPN− population appear not to be immunosuppressive." (PMID 38158643, 2024). "The results showed that PDPN-targeted NIR-PIT produced significant anti-tumour effects in mouse model of MPM." (PMID 39498336, 2024). "For example, combination therapy of cancer‐specific anti‐PDPN CAR‐T cells with oncolytic herpes virus inhibited tumor growth and improved survival in GBM." (PMID 38470096, 2024). "For example, the Src tyrosine kinase uses the focal adhesion adaptor protein Cas/BCAR1 to induce PDPN expression, consequently facilitating tumor cell motility." (PMID 39682237, 2024). "Podoplanin (PDPN) expressed on tumour cells interacts with platelet C-type lectin-like receptor 2 (CLEC-2)." (PMID 38561690, 2024).
tumor (continued). "Female patients had significantly longer overall survival and survival on TKIs, associated with higher tumor expression of endothelial Ang2 and LEC podoplanin." (PMID 39061998, 2024). "CLEC-2 is a physiological target protein of PDPN, implying that it is involved in PDPN-induced platelet aggregation, tumor metastasis, and other cellular responses related to PDPN." (PMID 38504248, 2024). "Overexpression of PDPN is observed not only in tumor cells but also in tumor stroma, including CAFs and immune cells." (PMID 39487962, 2024). "Platelets are often bound to tumor cells through the C-type lectin-like immune receptor 2 pathway that includes interaction with podoplanin expressed on several digestive tumors and is positively associated with poor prognosis." (PMID 38434966, 2024). "For instance, PDPN promotes tumor metastasis and progression by activating platelets after binding to CLEC-2." (PMID 38504248, 2024). "Quantification of the labelled tumour cells in lung cryosections at different time points after injection showed that the number of PDPN + cells was significantly higher than the number of PDPN- cells at all time points." (PMID 38561690, 2024). "The observations that the vast majority of tumor emboli in Mary-X fall within lymphatic channels were confirmed by companion podoplanin, LYVE1, and Prox1 immunocytochemical studies." (PMID 39669476, 2024). "In lesions showing localized expression of podoplanin, the outside layer of the tumor cells showed positive staining, but the inner cell nests showed no staining at all." (PMID 39541328, 2024). "When podoplanin on tumour cells interacts with CLEC-2 on platelets, Syk is phosphorylated by the interaction of the YxxL sequence on the CLEC-2 cytosolic tail with the SH2 tandem domains on Syk." (PMID 38561690, 2024). "The PDPN-induced platelet aggregation plays critical roles in tumor cell survival in circulation and hematogenous metastasis through the evasion from antitumor immunity and promotion of embolization." (PMID 39594582, 2024). "Whole blood was collected from the retro-orbital sinus before PDPN + and PDPN- tumour cell injection and 3 min after injection." (PMID 38561690, 2024). "We propose that such tumor suppressors and signaling pathways are involved in PDPN‐positive CAF in HGNEC." (PMID 39487962, 2024). "PDPN+ CAFs decreased over tumor progression, and were rarely present in metastases, and displayed longer cell morphology." (PMID 38525245, 2024). "We used the Syk inhibitor R406 to block platelet binding to tumour cells to assess the role of Syk in the PDPN-CLEC-2 interaction." (PMID 38561690, 2024). "Tumor-proximal fibroblasts, primarily myofibroblasts expressing podoplanin (PDPN) and enriched in Wnt ligand signaling, were identified." (PMID 38540204, 2024). "The identified association between PDPN overexpression and the facilitation of macrophage M2 polarization and neutrophil degranulation underscores the immunomodulatory impact of PDPN within the tumor microenvironment." (PMID 38275409, 2024). "PDPN transcription can also be governed by other cytokines and transcription factors over the course of tumor progression." (PMID 40741180, 2024). "Platelet aggregation-inducing factor, podoplanin, frequently upregulated on tumour cell surfaces, was found to not only trigger the formation of tumor–platelet crosstalk but also facilitate EMT by inducing TGF-β release from platelets." (PMID 38891849, 2024). "The binding of CD9 to tumor cells via PDPN reduces platelet aggregation and inhibits PDPN-induced metastasis in a mouse model of pulmonary metastasis." (PMID 40741180, 2024). "CLEC-2 on the surface of platelets was identified as a receptor for podoplanin and induces platelet aggregation in the tumour metastasis process." (PMID 38561690, 2024). "In oral squamous cell carcinoma, Mei and colleagues demonstrated that the ErbB3-binding protein-1 (EBP1) acts as a transcription factor that boosts PDPN transcription during tumor progression." (PMID 40741180, 2024).
tumor (continued). "PDPN levels are increased in stromal cells of the tumor microenvironment, including lymphatic endothelial cells, immune cells, and cancer-associated fibroblasts (CAFs); these non-malignant cells have diverse roles in cancer progression." (PMID 40741180, 2024). "PDPN expressed on the surface of some tumour cells has been reported to contribute to cancer pathogenesis by promoting tumour cell invasion and spreading." (PMID 38561690, 2024). "Overexpressed PDPN is reported to be associated with the immunosuppressive tumor microenvironment in GBM, characterized by the interplay between PDPN and M2 macrophage or neutrophil degranulation." (PMID 38470096, 2024). "In cancer, although the interaction between CLEC-2 and podoplanin-expressing tumor cells promote angiogenesis, tumor growth and metastasis, the expression of this receptor in gastric cancer cells suppresses metastasis." (PMID 39482490, 2024). "Podoplanin on tumour cells has been shown to promote pulmonary metastasis by inducing platelet aggregation." (PMID 38561690, 2024). "In the future, finding the downstream pathways of PDPN leading to tumor metastasis will be crucial for developing effective drugs against PDPN." (PMID 38504248, 2024). "The FAP mRNA levels showed a significant positive correlation with the ACTA2, COL11A1, TNC, and PDPN genes in PanCK(-) AOIs at EOCC tumor invasive margin." (PMID 37964075, 2023). "Some polyphenols, such as epigallocatechin-3-gallate and curcumin, have been reported to suppress PDPN expression in mouse tumours." (PMID 37755981, 2023). "For example, PDPN promoted tumour cell metastasis through activating platelet C‐type lectin‐like receptor 2 via induction of tumour cell‐induced platelet aggregation." (PMID 36156321, 2023). "High expression of PDPN on OS tumor cells has been correlated with poor prognosis and has shown to be dominantly expressed in metastasis over primary tumors." (PMID 36769180, 2023). "Platelet aggregation induced by PDPN-expressing tumor cells was shown to play a role in tumor growth and metastasis." (PMID 38067218, 2023). "Immunohistochemical staining with anti-endomucin and anti-podoplanin antibodies showed reduced tumor angiogenesis and lymphangiogenesis, respectively, in SAP30-KO mice." (PMID 37655663, 2023). "Facilitated EMT process and migration as a consequence of upregulated PDPN abundance in the selected brain-metastasis cell model and liver metastatic mouse model in vivo further confirmed that PDPN promoted tumor invasion." (PMID 37898647, 2023). "PDPN is involved in tumor malignant progression through activation of tumor invasiveness, EMT, and stemness." (PMID 37894446, 2023). "The location of the PDPN immunoexpression within the invading islands of the tumor cells was compared within all grades of OSCC." (PMID 37273383, 2023). "Tumor-proximal fibroblasts comprise large populations of myofibroblasts, strongly expressed podoplanin, and were enriched for Wnt ligand signaling." (PMID 37350578, 2023). "Tumor-cell-derived podoplanin (PDPN) is also a key regulator of platelet activation and aggregation." (PMID 37569299, 2023). "Interaction with cancer cell podoplanin through CLEC-2 on platelets is another way through which platelets induce EMT in tumor cells." (PMID 37770941, 2023). "PDPN expressed in CAFs contributes to overall tumour growth due to TME‐mediated angiogenesis and immunosuppression." (PMID 36156321, 2023). "PDPN-expressing tumor cells activate the ability of platelets to activate the C-type lectin-like receptor 2 (CLEC-2)." (PMID 36769180, 2023). "Patients with a poor outcome expressed PDPN broadly across the tumor microenvironment whilst HIF-1α and VEGF expression also extended into the distal stromal and immune regions and likely indicates more extensive hypoxia in this subgroup." (PMID 37350578, 2023).